TRAV8-7 (T cell receptor alpha variable 8-7 (pseudogene))
Gene: T-cell receptor variable (V) gene on chromosome 14 (22,132,553 to 22,133,034, forward strand). Ensembl gene ENSG00000211808.
Gene Ontology:
Biological process: adaptive immune response
Cellular component: immunoglobulin complex; plasma membrane
Homologues: Paralogues in human: TRAV8-3 (66% identical), TRAV8-4 (65% identical), TRAV8-2 (64% identical), TRAV8-6 (61% identical), TRAV8-1 (60% identical), TRAV3 (56% identical), TRAV16 (48% identical).